GPC1 (glypican 1)
Diseases named in the same sentence as GPC1 in open-access papers (continued):
Sharing a sentence is not in itself a finding about the gene and the disease.
prostate carcinoma (continued). "Kaplan–Meier curve analysis showed a positive correlation between the GPC-1 expression and the survival rate in prostate cancer patients." (PMID 33927256, 2021). "GPC1 has been proposed to represent a biomarker for prostate cancer, with better efficiency than the prostate-specific antigens (PSA)." (PMID 33947326, 2021). "This study also showed that human foreskin fibroblasts exposed to conditioned media from prostate cancer cells in which GPC-1 was inhibited exhibited an increase in mRNA expression of several genes involved in fibroblast activation." (PMID 33927256, 2021). "It is to be noted that our initial studies demonstrated an increase in GPC-1 expression in HS-5 cells following an acute exposure to prostate cancer CCM." (PMID 33927256, 2021). "The effect of GPC-1 inhibition on HS-5 cell migration after exposure to prostate cancer CCM was analyzed using a scratch wound healing assay." (PMID 33927256, 2021). "Suhovskih and colleagues detected GPC1 for the first time in prostate cancer in 2013, event that indicates the need of investigation regarding this molecule on the disease progression." (PMID 33947326, 2021). "GPC1 and GPC5 were predominantly expressed in the normal prostate cell line RWPE-1, whereas GPC1 was the primary member observed in the prostate cancer cell lines PC-3 and DU-145." (PMID 33947326, 2021). "Data in this study support the conclusion that the exposure of prostate cancer cells to CCM from HS-5 cells in which GPC-1 was inhibited increases the acquisition of a mesenchymal phenotype and increases the rate of cell migration after wound healing." (PMID 33927256, 2021). "GPC-1 induced an activated fibroblast phenotype when HS-5 cells were exposed to prostate cancer cell conditioned media (CCM)." (PMID 33927256, 2021). "Further, studies are needed to determine the specific cell types and assess overall protein expression levels, as well as the effect of genetic manipulation of GPC-1 expression on bone remodeling induced by prostate cancer." (PMID 33927256, 2021). "The effect of GPC-1 inhibition on MTT staining in HS-5 cells when exposed to CCM from prostate cancer cells was determined." (PMID 33927256, 2021). "It is possible that exposure of HS-5 cells to prostate cancer CCM induced a compensatory mechanism to retain GPC-1 in HS-5 cells to prevent BSC switch to activated fibroblasts." (PMID 33927256, 2021). "Collectively, our data suggest that in addition to supporting the intrinsic phenotypic characteristics in BSCs, GPC-1 also regulates their extrinsic phenotype to support the activated fibroblasts’ ability to increase prostate cancer cell migration and EMT." (PMID 33927256, 2021). "Glypican-1 is a heparan sulfate proteoglycan that is overexpressed in prostate cancer (PCa), and a variety of solid tumors." (PMID 33302918, 2020). "To assess the ability and specificity of MIL-38-CD3 to induce T cell killing of GPC-1-expressing prostate tumour cells, we chose two clinically relevant prostate cancer cell lines for assessment of T cell killing." (PMID 33302918, 2020). "In conclusion, our findings demonstrate that molecular inhibition of GPC-1 has paradoxical effects on prostate cancer cell and tumor growth." (PMID 31391540, 2019). "Current studies have focused primarily on the differential expression of GPCs in prostate cancer tissue, and at least GPC-1 and −5 have been suggested to correlate to tumor aggressiveness." (PMID 31391540, 2019). "GPC-1 mRNA was highly expressed in primary prostate epithelial cells and metastatic prostate cancer cells (DU-145 and PC-3)." (PMID 31391540, 2019). "One recent study even proposed GPC-1 as a biomarker for prostate cancer and demonstrated high expression of GPC-1 in DU-145 cells." (PMID 31391540, 2019). "We observed high expression of GPC-1 in more aggressive prostate cancer cell lines such as PC-3 and DU-145." (PMID 31391540, 2019).
prostate carcinoma (continued). "We addressed this gap-in-knowledge by determining the differential expression of GPCs in several prostate cancer cells, which demonstrated increased expression of GPC-1 in more metastatic cells." (PMID 31391540, 2019). "Only GPC-5 and GPC-1 have been studied in prostate cancer, and those studies mainly focused on gene expression and localization in human prostatic tissues via in vitro experiments using a single cell culture." (PMID 31391540, 2019). "To determine the correlation between GPC-1 expression and prostate cancer in humans we assessed the TCGA Prostate Cancer Cohort in which samples were collected at the primary tumor sites and only mRNA expression data are available." (PMID 31391540, 2019). "In the urinary sediment samples from 125 patients with prostate cancer and a group of healthy individuals, the sensitivity and specificity of GPC-1 achieved 71 and 76%, respectively." (PMID 31355137, 2019). "The MIL-38 antibody targets GPC-1 on several prostate cancer cell lines and, importantly, on prostate cancer tissue." (PMID 29672570, 2018). "Detection of GPC-1 discriminated between the prostate cancer cohort and the combined cohorts of BPH and normal control specimens with a sensitivity and specificity of 71% and 73%, respectively." (PMID 29672570, 2018). "Our findings strongly promote future investigation into the use of glypican-1 for early detection of prostate cancer." (PMID 29854284, 2018). "For example, the serum GPC1 levels were higher in hepatocellular carcinoma (P < 0.001), cholangiocarcinoma (P < 0.001), gastric carcinoma (P = 0.019), and prostate cancer (P = 0.01) than in HC." (PMID 30358133, 2018). "Sensitivity and specificity of GPC-1 detection for prostate cancer in cell sediments from patient urine samples using MIL-38: Comparison of prostate cancer samples with BPH and normal samples." (PMID 29672570, 2018). "While technically challenging, the detection of GPC-1 using the MIL-38 IFA assay described here shows promise for improving detection of prostate cancer beyond the current standard PSA." (PMID 29672570, 2018). "The use of MIL-38 to detect GPC-1 by IFA discriminated between prostate cancer and BPH urine specimens with a sensitivity and specificity of 71% and 76%, respectively." (PMID 29672570, 2018). "Glypican-1 is an another proteoglycan, which expression was detected in prostate cancer for the first time." (PMID 23691363, 2013). "As the loss of GPC-1 recapitulated several intrinsic features of CAF behavior in HS-5 cells, we next determined how GPC-1 regulates the phenotypic and functional behavior of HS-5 cells when exposed to a model of the prostate cancer TME in the form of CCM." (PMID 33927256, 2021). "Hence, our novel findings regarding the functions of GPC-1 in managing the intrinsic and extrinsic CAF phenotypes of BSCs in prostate cancer are important as they suggest GPC-1 as a novel anti-CAF target in prostate cancer." (PMID 33927256, 2021). "Furthermore, this same study showed that treatment of fibroblasts and human MSCs with conditioned media isolated from prostate cancer cells in which GPC-1 was inhibited, increased the expression of genes, proteins and enzymes known to facilitate tumor growth." (PMID 33927256, 2021). "GPC-1 inhibition in HS-5 cells increased gap closure after exposure to CCM from either DU-145 or PC-3 cells after 48 h, as compared to control HS-5 cells, indicating that GPC-1 inhibition in HS-5 cells increased their migration when exposed to prostate cancer CCM." (PMID 33927256, 2021). "However, migration rates were further increased, and the cells migrated as a cohort when treated with prostate cancer CCM after GPC-1 inhibition." (PMID 33927256, 2021). "In addition, exosomal proteins have been found as potential diagnostic markers in various tumors, namely a few typical ones: CEA (colorectal cancer), Her2 (breast cancer), Glypican-1 (breast/ pancreatic/prostate cancer), PSA (prostate cancer)." (PMID 32751565, 2020).
prostate carcinoma (continued). "Also surprisingly, it increases cancer cell proliferation and migration in aggressive prostate cancer cell line DU-145 cells, suggesting that GPC-1 accounts for among the factors that drive a cell line-dependent response to stromal cells." (PMID 33299638, 2020). "Assessment of the effect of GPC-1 inhibition on gene expression in stromal cells provide some of the first evidence suggesting that GPC-1 may act a tumor suppressor in prostate cancer via its interaction with the stromal cells." (PMID 31391540, 2019). "The opposing roles of GPC-1 in these prostate cancer cells may be regulated by other receptors (Sonic Hedgehog66 and FGFRs67) which can be differentially expressed in these two cell types." (PMID 31391540, 2019). "GPC-1 expression was also higher in neuroendocrine derived prostate cancer cells, DU-14513." (PMID 31391540, 2019). "In contrast, GPC-1 expression has been reported to be elevated in prostate cancer patients." (PMID 31391540, 2019). "Taken together, these reports suggest that GPC-1 might be a useful marker for the diagnosis of prostate cancer." (PMID 31355137, 2019). "The differential effects of TCM isolated from GPC-1 inhibited cells on tumor stromal cell gene expression further support the hypothesis that GPC-1’s role in prostate cancer includes mediating interactions with the TME." (PMID 31391540, 2019). "Circulating GPC-1 was reduced in prostate cancer patients vs. non- prostate cancer patients." (PMID 31355137, 2019). "Furthermore, inhibition of GPC-1 decreased several markers of prostate cancer aggression, such as MMP-9, E-Cadherin (E-Cad), N-Cadherin (N-Cad), CXCR4, vimentin (VIM), Zeb1 and Zeb238–40, as determined using qRT-PCR." (PMID 31391540, 2019). "Collectively, these data support the hypothesis that GPC-1 mediates the growth and migration of prostate cancer cells in vitro." (PMID 31391540, 2019). "This alteration suggests that some of the effects of GPC-1 in prostate cancer may be mediated by interaction with the tumor microenvironment." (PMID 31391540, 2019). "This could be assessed using a modified IFA assay able to quantify GPC-1 fluorescent signal, and normalising to prostate cancer cell content using PSA expression (as is used for normalization in the PCA3 test)." (PMID 29672570, 2018). "The combined use of GPC-1 with other known urine biomarkers for prostate cancer may improve the detection of prostate cancer beyond the use of PSA alone." (PMID 29672570, 2018). "The results described herein demonstrate the potential of GPC-1 as a biomarker for prostate cancer." (PMID 29672570, 2018). "The odds ratio (OR) and 95% confidence intervals (CIs) for GPC-1-positive cells in patients with prostate cancer, adjusted for PSA, was greatest at the lowest serum PSA (<2 ng/ml; OR = 13.4; 95% CI: 4.0–44.7) compared with no adjustment for PSA (OR = 6.4; 95% CI: 2.8–14.9)." (PMID 29672570, 2018). "Collectively, it is likely that GPC-1 may play a protective role in prostate cancer." (PMID 31391540, 2019). "Our observation of the paradoxical behaviors in prostate tumor growth between in vitro and in vivo models led us to hypothesize that inhibition of GPC-1 expression in prostate cancer cells remodeled the TME and subsequently affected tumor growth by mediating cancer-stromal cell interactions." (PMID 31391540, 2019). "The use of MIL-38 for detection of GPC-1 may be a useful tool for detection of prostate cancer." (PMID 29672570, 2018). "Thus, detection of GPC-1 on prostate cancer cells using MIL-38 may be a useful tool for the diagnosis of prostate cancer." (PMID 29672570, 2018). "Thus, we hypothesized that detection of GPC-1 in urine cellular material may identify individuals with prostate cancer." (PMID 29672570, 2018).
prostate carcinoma (continued). "However, in prostate tumours, there was a significant decrease in syndecan-1 and glypican-1 protein expressions in prostate cancer epithelial cells with the simultaneous increase of overall content of the proteoglycans in the stromal compartment of prostate tumour tissue." (PMID 23691363, 2013). "Thus, GPC1 may be a candidate target molecule for NIR-PIT in prostate cancer." (PMID 35740662, 2022). "Miltuximab® targets glypican-1 (GPC-1), a cell surface protein involved in tumour growth, which is overexpressed in solid tumours, including prostate cancer (PCa)." (PMID 32382920, 2020). "Recent studies suggest that glypican-1 (GPC-1) is a biomarker for prostate cancer, but there are few studies elucidating the role of GPC-1 in prostate cancer progression." (PMID 31391540, 2019). "The MIL-38 monoclonal antibody is specific for the membrane glycoprotein glypican 1 (GPC-1) and binds to prostate cancer tissue." (PMID 29672570, 2018). "The role of GPC-1 is further supported by the fact that no significant change was seen in the migration of wild-type HS-5 cells after treatment with prostate cancer CCM." (PMID 33927256, 2021). "This study suggested that the lack of GPC-1 in prostate cancer cells induces a more reactive tumor stroma in vivo." (PMID 33927256, 2021). "The role of GPCs, specifically GPC-1, in prostate cancer cells and stroma signaling exchange has not yet been studied." (PMID 31391540, 2019). "Employing a novel assay to assess the presence of GPC-1 in UCS by use of MIL-38 staining and detection by IFA, prostate cancer patients could be distinguished from normal controls and patients with BPH." (PMID 29672570, 2018). "We report here the use of MIL-38 recognition of GPC-1 in UCS to distinguish between patients with prostate cancer and those with no cancer (both normal controls and patients with benign prostatic hyperplasia or hypertrophy (BPH)." (PMID 29672570, 2018). "However, in our study, we did not see any changes in the PC-3 cell proliferation following treatment with HS-5 CCM after GPC-1 inhibition, suggesting that GPC-1 plays a selective role in the paracrine activation of prostate cancer cells in the bone microenvironment." (PMID 33927256, 2021). "Using this assay, we show for the first time that circulating glypican-1 levels can differentiate non-cancer (normal and benign prostatic hyperplasia) patients from prostate cancer patients, as well as benign prostatic hyperplasia patients alone from prostate cancer patients." (PMID 29854284, 2018). "The detection of GPC-1 in urine or blood, perhaps in combination with PSA and/or other biomarkers, may provide clinical benefit in terms of less invasive testing, earlier and more accurate detection of prostate cancer, and decrease the number of unnecessary biopsies." (PMID 29672570, 2018). "While our recent study suggested that GPC-1 acts as a tumor suppressor, it is not known if GPC-1 plays a direct role in modulating the activation of stromal cell components, such as fibroblasts, in prostate cancer." (PMID 33927256, 2021). "Despite studies suggesting that GPC-1 expression is altered in prostate cancer, and studies suggesting that GPC-1 may be a marker of aggressive prostate cancer, there are little to no studies assessing the functional role of GPC-1 in prostate cancer cell growth or tumorigenesis." (PMID 31391540, 2019).
glioma (22 papers, 2012 to 2025). A benign or malignant brain and spinal cord tumor that arises from glial cells (astrocytes, oligodendrocytes, ependymal cells). "Some studies reported that high GPC-1 expression was associated with poor outcomes of PC and glioma, and the loss of GPC-1 results in reduced tumor growth, angiogenesis, and metastasis." (PMID 36313694, 2022). "Collectively, these results suggest that GPC1 alone cannot act as a strong and stable prognostic indicator for glioma, although GPC1 was implicated in the proliferation of glioma cells." (PMID 33712571, 2021). "Then, an association analysis was performed between ANXA2 and GPC1 expression and the clinicopathological features of glioma patients." (PMID 33712571, 2021). "Overexpression of GPC1 is a hallmark of breast cancer, esophageal squamous cell carcinoma, and gliomas." (PMID 32916872, 2020). "Notably, ANXA2-induced GPC1 overexpression, in turn, caused a sustained upregulation of c-Myc, leading to enhanced glioma cell proliferation." (PMID 33712571, 2021). "It has been shown that the expression of Glypican-1 is increased by Annexin A2 through a positive feedback loop with c-Myc that ultimately promotes glioma cell proliferation." (PMID 38272115, 2024). "A recent study showed that overexpression of Annexin A2 (Anxa2) increased the expression of Glypican 1 (Gpc1) via c-Myc, creating a positive feedback loop that enhances proliferation of glioma cells." (PMID 35223842, 2022). "In cancer tissues of esophageal squamous cell carcinomas, cervical cancers, and glioma, GPC1 expression levels were higher than those in normal tissues." (PMID 36158119, 2022). "In 90 tumors (Cohort 1), we found that both ANXA2 and GPC1 were more highly expressed at the mRNA level in the glioma samples than in the peritumoral tissues." (PMID 33712571, 2021). "Intriguingly, a positive relationship between ANXA2 and GPC1 was demonstrated at both the mRNA and protein levels in glioma tissues." (PMID 33712571, 2021). "The overexpression of both ANXA2 and GPC1 in tumors was reconfirmed by western blot analyses of 6 paired glioma samples selected from the 90 glioma cases." (PMID 33712571, 2021). "Both mRNA and protein levels of ANXA2 were upregulated in glioma tissues and coincided with the overexpression of GPC1." (PMID 33712571, 2021). "The ANXA2 and GPC1 mRNA expression of 90 paired glioma samples in Cohort 1 was measured by qRT-PCR analysis." (PMID 33712571, 2021). "Most importantly, the combination of ANXA2 and its downstream target GPC1 can be used for improved prognostic evaluation in glioma patients." (PMID 33712571, 2021). "The knockdown of GPC1 significantly reversed the ANXA2-mediated proliferation of glioma cells and the upregulation of c-Myc." (PMID 33712571, 2021). "Then, GPC1 overexpression was performed in glioma cells by infecting them with GPC1-coding lentivirus to demonstrate the effect of GPC1 on proliferation." (PMID 33712571, 2021). "Conversely, glioma patients who expressed low levels of either ANXA2 or GPC1 had a better prognosis." (PMID 33712571, 2021). "In conclusion, ANXA2 promotes glioma cell proliferation by forming a positive feedback loop between GPC1 and c-Myc, indicating a potential and promising target for glioma treatment in future studies." (PMID 33712571, 2021). "The data suggest that ANXA2 induces a positive feedback loop involving GPC1 and c-Myc to amplify the proliferation of glioma cells." (PMID 33712571, 2021). "Similar to its role in glioma angiogenesis, GPC1 appears to be a specific HSPG actor in hair microvascular remodeling induced by growth factors." (PMID 34957110, 2021). "In view of the fact that GPC1 is more abundantly expressed in the brain, we focused our study on GPC1 and demonstrated that the proliferation of U118 glioma cells was promoted by GPC1 overexpression but weakened by GPC1 deletion." (PMID 33712571, 2021).